LIF (LIF interleukin 6 family cytokine)
Diseases named in the same sentence as LIF in open-access papers (continued):
Sharing a sentence is not in itself a finding about the gene and the disease.
tumor (continued). "Further growth in situ of this initial tumor would require implantation in the host and vascularization through the overexpression of some aspecific checkpoint molecules, such as CD44, ID, LIF, HSP70, and HLA-G." (PMID 34295890, 2021). "IHC staining revealed that positive expressions of Ki-67, LIF and p-STAT3 in tumor sections of mice with knockdown of LBX2-AS1 were significantly lower than those of controls." (PMID 34729101, 2021). "Leukemia inhibitory factor (LIF)—LIF is significantly upregulated in NSCLC tumors compared to adjacent tissues, and correlates with lymph node metastasis and advanced tumor stage." (PMID 34944848, 2021). "Tumor-promoting genes such as CXCL2 and LIF, as well as PDL1, a blocker of T-cell-based immune responses were downregulated." (PMID 33859739, 2021). "They express low level of αSMA but high levels of cytokines and chemokines such as IL-6, IL-11 and leukemia inhibitory factor (LIF) and promote tumor growth." (PMID 34290984, 2021). "LIF promotes aggressive tumor growth, and PDAC patients with high LIF mRNA levels have much worse overall survival than those with low LIF mRNA levels." (PMID 33846527, 2021). "Their interaction with the BMDMs and tumor cells in the collagen-I matrix increased production of GM-CSF, G-CSF, IL-6, CCL2, CCL3, CCL4 and CCL12, and reduced production of IFN-β1, LIF, VEGF, CCL17, CXCL5 and CX3CL1." (PMID 34572807, 2021). "They demonstrated that iCAF formation is induced by tumor-secreted IL-1 that activates a LIF/JAK/STAT-dependent cytokine cascade, whereas tumor-secreted TGF-β antagonizes JAK/STAT signaling by IL-1R1 downregulation and promotes differentiation into myCAF." (PMID 35004765, 2021). "In conclusion, according to the findings of this study LIF and LIFR can be considered in cancer targeted therapy, especially to fight with those tumors that express these proteins such as tumor-initiating cells." (PMID 32651426, 2020). "This is in accordance with the observed reduction of the pro-tumorigenic factors IL-6, periostin, LIF and, PGE2 which previously have been shown to promote tumour cell growth." (PMID 33060625, 2020). "OSM is a cytokine member of the leukemia inhibitory factor/oncostatin-M (LIF/OSM) family and a growth regulator with important roles in inflammation and tumor growth inhibition." (PMID 32286411, 2020). "IL-6, periostin, LIF, and prostaglandin E2 (PGE2), are CAF-derived soluble factors that have been described to play a role in tumour progression." (PMID 33060625, 2020). "Our findings indicated that immune-mediated blockage of LIF and LIFR delayed or event prevented tumor growth." (PMID 32651426, 2020). "It exerts tumor-suppressing effects through TGF-β-induced cell cycle arrest and inhibition of cell migration through the LIF/p21 signaling cascade pathway in cutaneous melanoma." (PMID 31973037, 2020). "To study the clinical relevance of LIF in patients with OSCC, we first examined LIF protein expression in paraffin-embedded tumor tissue specimens of patients with OSCC through immunohistochemical analysis." (PMID 31973037, 2020). "M2d macrophages induced by adenosine, leukemia inhibitory factor (LIF) and IL-6 are believed to induce angiogenesis to regulate tumor progression and enhance tumor survival." (PMID 31192126, 2019). "Because miRNAs can act either as tumor suppressors or oncogenes, depending on their target genes in different recipient cells, we identified three anti-angiogenesis genes (THBS1, STAT1, LIF) as target gene of miR-194." (PMID 31700002, 2019). "Accumulation of cytoplasmic LIF in NPC cells promoted EMT and invadopodia formation leading to enhanced damage of the HUVEC layer and increased vascular dissemination of tumor cells in zebrafish embryonic xenografts." (PMID 30504771, 2018).
tumor (continued). "It has more recently been demonstrated that LIF induces the expression of miRNA-21, a miRNA that promotes EMT through STAT3 signalling in human tumor cells and was shown in our ISH experiments to be expressed at similar levels in all three classes." (PMID 28415643, 2017). "The differentially expressed genes in triphasic tumours relative to blastemal tumours included genes published as potential UB/CD markers: MUC1, PKHD1, KRT7, CDH1, and LIF." (PMID 29040332, 2017). "As IFN-γ activates ZEB1, which in turn suppresses LIF expression, ZEB1 expression can be queried as a surrogate measure for therapies that invoke tumor differentiation." (PMID 28246407, 2017). "We first confirmed that ICAM-1 is induced by both LIF and TGFβ and showed that ICAM-1 expression in hDF is stimulated by tumor cells conditioned media." (PMID 27901489, 2017). "For example, IL10, LIF and IL1RA were similarly regulated in GBM tumor at transcript level as measured by RNase protection assay." (PMID 26390214, 2015). "Results show that LIF and LIFR expression were higher in neoplastic than in control cholangiocytes; LIF was also expressed by tumor stromal cells." (PMID 26296968, 2015). "On the other hand, we showed that both the CDSF medium used in the present study, which contains LIF, and the CDSF medium supplemented with Bmp4 poorly sustained the tumor-like growth of mESCs." (PMID 21731714, 2011). "Plasma analyte profiling of both moderately and severely cachectic mice revealed that circulating levels of IL-6 and three other gp130 ligands, IL-11, leukemia inhibitory factor (LIF) and Oncostatin M were significantly increased in tumor-bearing mice." (PMID 21799891, 2011). "Therefore, the different biological activity displayed by LIF on normal cells and tumor cells might be due to the altered biological response that tumor cells develop to the activation of certain signaling pathways rather than to a differential effect of this cytokine on its intracellular mediators." (PMID 17925034, 2007). "Furthermore, a cluster of cytokines (LIF, SDF-1, HGF, SCGFb) was identified as potentially involved in the regulation of PD-L1 expression by tumor cells." (PMID 41597220, 2026). "While preliminary research into the anti‐tumor mechanism of SH in HCC has focused on its role in inhibiting LIF expression, it has not been definitively established that SH directly targets LIF, rendering it an LIF modulator instead of an LIF inhibitor." (PMID 40416597, 2025). "In summary, we identified LIF as a tumor promoter in HCC and systematically investigated its oncogenic role in facilitating cancer cell growth and metastasis by modulating mitophagy through a new signaling pathway of LIF/p38MAPK/p62." (PMID 40416597, 2025). "In addition, ectopic LIF overexpression in HCC cells reversed the CVB‐D‐induced phosphorylation of p38MAPK at the Thr180/ Tyr182 sites and reversed the anti‐tumor effect of CVB‐D, demonstrating that LIF is a potential druggable target of CVB‐D." (PMID 40416597, 2025). "Notably, the highest LIF expression was observed in high‐grade adenocarcinomas in grade III and correlated with increased tumor severity." (PMID 41163398, 2025). "In addition, plasma levels of LIF protein were significantly upregulated in all the allograft models of LLC, RM1, MC38, or 4T1 cells, as well as in the tumor-bearing MMTV-PyMT mice." (PMID 38467743, 2024). "Furthermore, CAFs secrete various cytokines, exosomes, and growth factors, such as leukemia inhibitory factor (LIF) and growth differentiation factor 15 (GDF15), which further drive tumor growth and invasion." (PMID 38920700, 2024).
tumor (continued). "Meanwhile, we found that the plasma LIF or Gal3 levels of tumor-bearing mice were not affected by the exogenous NE treatment, confirming that the release of LIF or Gal3 by cancer cells was independent of sympathetic signaling." (PMID 38467743, 2024). "Furthermore, 1G11 inhibited LIF-induced p-STAT3 in vitro, and reduced p-STAT3 levels in tumor cells in tumor-bearing mice, thereby inhibiting tumor growth." (PMID 39169307, 2024). "Specifically, LIF and GM-CSF secretion was PKD-dependent in the metastatic cell lines MDA-MB-231, MDA-MB-468 and MDA-MB-436, compared to one primary tumor cell line while the secretion of IL-11 and MMP-13 was found to be regulated by PKD only in metastatic TNBC cells." (PMID 38323010, 2024). "On the other hand, although a single injection of 2 ng LIF led to its plasma levels comparable to those of the tumor-bearing conditions, this low dose was not sufficient to elicit brain activation." (PMID 38467743, 2024). "We then performed cell viability assays using 24 OCa cell lines representing four different subtypes of OCa including 12 established, six primary tumor derived and six ascites-derived OCa cell lines to see if addition of LIFR inhibitor EC359 blocks LIF/LIFR autocrine signaling." (PMID 38789520, 2024). "A very similar decrease in hepatic de novo lipogenesis was observed in the mice bearing C26 tumors but not C26-LIF KO tumors at similar sizes, suggesting that tumor-secreted LIF inhibits hepatic de novo lipogenesis in mice." (PMID 38245529, 2024). "Emergent research illuminates that LIF, an immunomodulatory signaling molecule, might operate as a critical effector downstream of the TGF-β/Smad2/3 pathway, furnishing a pivotal axis in tumor immunoresponsivity and potentially metastasis." (PMID 38490994, 2024). "However, they significantly differed in terms of marker genes (AKR1C1, FOSL1, LIF, and THAP2 vs. WNT5A, GREM1, TNC, and MMP1), tissue origins (normal vs. tumor), and organ preferences." (PMID 38744958, 2024). "Accordingly, our data supports several alternative approaches for inhibiting immune-modulatory pSTAT3+ myMAFs, including progranulin, LIF, and osteopontin, which warrants further investigation for combination with ICT to further harness and unleash the anti-tumour immune response." (PMID 38678021, 2024). "A prominent SE region (chr22:30581493‐30659814) near LIF (hereafter named as LIF‐SE) stood as a prominent and functionally untapped SE in HNSCC as its presence and highest ranks across all HNSCC cell lines examined and the absence in non‐tumor cells." (PMID 39206755, 2024). "Further, there was no significant change in plasma LIF or Gal3 levels of the tumor-bearing mice with sympathetic ablation." (PMID 38467743, 2024). "We analysed the intercellular networks about LIF/LIFR and found that interactions occurred frequently between TM4SF1+ tumor cells and proliferative tumor cells, indicating that LIF were mainly secreted from TM4SF1+ or proliferative tumor cells exerted an effect on other cell types." (PMID 37360193, 2023). "Notably, besides its angiogenic properties, LIF is known to regulate CD206 (a marker for TAM-M2 cell polarization) and to prevent CD8+ T cell tumor infiltration, compromising responses to anti-PD-1 therapy." (PMID 36934257, 2023). "In some GBM-derived CSCs, LIF has been shown to have self-renewal activity, and blocking LIF signaling leads to tumor regression, but this effect is not general in GBM." (PMID 38137514, 2023). "Elevated CLCF1 and LIF levels may lead to STAT3 activation, which enhances tumor cell proliferation, including HCC." (PMID 37777158, 2023). "Five cytokines (IL-10, KC, LIF, MIP-2, and VEGF) involved in tumorigenesis, angiogenesis, and chemoattraction of immune cells were found to have significant positive correlations with tumor volume." (PMID 35681702, 2022).
tumor (continued). "Moreover, studies have suggested that several CAF-derived cytokines, including IL6 and LIF, can induce an EMT phenotype in tumor cells and an immune evasion in the tumor microenvironment to promote tumor progression in murine PDAC models." (PMID 35805064, 2022). "p300, BMP, PAX6 (anti-GBM override), HOPX (tumor suppressive + differentiation), NRSF/REST (astrcytogenic but capable of playing oncogenic role), LIF, and TGF beta: BMP is also involved in the neuronal development but it primarily has far greater gliogenic role." (PMID 35538578, 2022). "They suggested that the use of LIF-inhibitors might suppress PANR, limit tumor spread, and increase patients’ quality of life." (PMID 35565450, 2022). "Interestingly, we noticed that LIF and CCL2 was tightly correlated with mesenchymal subtype tumor focus in mGBM and predicted poor survival of GBM patients." (PMID 34987659, 2022). "Given the redundancy in IL6/LIF signaling through the GP130 coreceptor and downstream JAK/STAT signaling cascade, tumors were scored as positive if they expressed either cytokine in the tumor microenvironment." (PMID 36230597, 2022). "Despite this, recent insights into their functional roles in cancer have highlighted interesting patterns that may allude to a broader understanding of LIF and LIFR within tumor growth and metastasis." (PMID 34395259, 2021). "The results indicate that the mean HSCORES of FGF18, IL23A, and LIF in tumor tissues were significantly higher than those in normal tissues (p < 0.05), while the opposite trend was observed for SLIT2." (PMID 34017356, 2021). "Although the mechanism of LIF expression by CAFs is still unknown, a recent study claimed that TGF-β could stimulate LIF secretion in tumor cells and fibroblasts." (PMID 34947829, 2021). "This is not to say that LIF and LIFRβ are not relevant; however, but rather that the focus of the conversation surrounding them in cancer should be shifted towards how LIF and LIFR can be understood through the lens of tumor suppression and promotion via the less understood Hippo pathway." (PMID 34395259, 2021). "CAF with tumor-promoting functions secrete growth factors (HGF, IGF1, CTGF, PDGF, VEGF, LIF), cytokines (IL-1, IL-4, IL-6, IL-8, IL-10, TGF-β), and chemokines (CCL2, CCL5, CXCL5, CXCL9, CXCL10, CXCL12), WNT5α, and bone morphogenic protein 4 (BMP4), which promote tumor progression." (PMID 35008832, 2021). "Finally, results of ongoing clinical trials will provide some insights regarding the value of LIF as therapeutic target in PDAC and other tumor types." (PMID 33630157, 2021). "In addition, at the protein level, FGF18, IL23A, LIF, and VGF stained more deeply in tumor tissues than in normal tissues, while CCL28 and SLIT2 were only deeply stained in normal intestinal mucosal tissues according to the Human Protein Atlas." (PMID 34017356, 2021). "The role of LIF signaling in cancer progression appears to be tumor-type dependent, although this does not resolve all of the controversy." (PMID 32023849, 2020). "Interestingly, while LIF is known to activate the same downstream signaling pathways as OSM and IL-6, STAT3 appears to play a contradictory role in the context of tumor cell dormancy in the bone." (PMID 32023849, 2020). "For example, leukemia inhibitory factor (LIF) promotes the infiltration of CD163+CD206+ M2 macrophages, and the blockade of LIF in LIF-expressing tumors increases the production of CXCL9, attracting cytotoxic CD8+ T cells to the tumor site." (PMID 32707850, 2020). "JAKs are key participants in signaling networks fueled by a variety of cytokine and growth factor receptors in the tumor microenvironment, including IL-6, IL-11, IL-27, interferon (IFN-α/β/γ) oncostatin M (OSM), leukemia inhibitory factor (LIF), epidermal growth factor (EGF) and others." (PMID 29190997, 2017).
tumor (continued). "The somatic cells of the testes secrete paracrine factors such as SCF, retinoic acid, FGF2, LIF, EGF and GDFN as well as androgenic hormones, and these might play a role in providing a tumor-promoting environment in the mouse." (PMID 22655094, 2012). "We found that all those cells express LIF, although tumor cells tend to show higher levels than non-tumorigenic ones." (PMID 17925034, 2007). "Multiple lines of transcriptomic evidence in tumor-educated THP1 cells point to STAT3 pathway activation, including upregulation of canonical STAT3 targets (SOCS3, CISH, BCL3, JUNB, PIM1) and increased expression of STAT3-activating ligands (IL6, IL11, LIF, OSM) in response to TNBC contact." (PMID 41514627, 2025). "Monotherapy with anti-LIF, anti-PD-L1, or chemo did not significantly control tumor growth." (PMID 39857986, 2025). "In addition, the knockout of leukemia inhibitory factor (LIF), another IL-6 family cytokine proposed as a cachectic factor in the model, also affected tumor growth but not cachexia." (PMID 38671295, 2024). "LIF epigenetically blocks the chemokine MIG (CXCL9), which is involved in the polarization of macrophages along the M1 pathway and ensures the recruitment of cytotoxic CD8+ T cells into the tumor, which have an antitumor effect; hence, a decrease in the level of LIF causes tumor regression." (PMID 38891915, 2024). "However, we cannot confidently determine the source of LIF which plays a dominant role in stemness control, and cannot rule out that LIF from other cell types in tumor microenvironment promotes HNSCC stemness." (PMID 39206755, 2024). "Functional studies in transgenic mouse models of PDAC revealed that paracrine activation of the LIF-LIFR-GP130 signaling complex was crucial in modulating EMT status and cancer cell differentiation, and blocking this signaling complex significantly reduced tumor growth and prolonged survival time." (PMID 37209817, 2023). "To examine whether the combination of IL-1α and LIF in the absence of G-CSF is relevant to human disease, we reexamined human tumor RNA-sequencing datasets from TCGA and other sources." (PMID 37134077, 2023). "The reduction of LIF production in CAF by Ent lowered the pro-tumorigenic crosstalk mediated by LIF and the tumor LIFR-STAT3 pathway, phenocopying the effect of LIF blockade and potentially contributing to tumor progression arrest and sensitization to chemotherapy." (PMID 38057326, 2023). "Thus, LIF and CCL2 might be responsible for high percentage of mesenchymal subtype tumor focus in mGBM and the two cytokines could help diagnosis of molecular subtypes of GBM in histopathological examination." (PMID 34987659, 2022). "Leukemia inhibitory factor (LIF) is a 180 amino acids length protein that is found in many cells, including fibroblasts, activated T cells, macrophages, chondrocytes, bone marrow stromal cells, mesenchymal stem cells, endothelial cells, astrocytes, and tumor cells." (PMID 36284106, 2022). "Interestingly, we revealed the dual mechanism of circRNA in the cytoplasm; this was the study report to reveal that circFARP1 accurately and cooperatively regulates the expression and secretion of LIF, implying that circRNAs collaborate in the TME to drive tumor chemoresistance." (PMID 35045883, 2022). "Collectively, these results indicated that LIF was produced by CAFs but not by tumor cells." (PMID 35045883, 2022). "Although the exact mechanism of this tumor-initiated transformation of fibroblasts is unknown, some studies suggest that direct cell–cell contact, as well as cell-derived soluble factors such as TGF-beta and LIF may play an important role in the this process." (PMID 32328671, 2021). "This study also noted that several gp130 cytokines (IL-6, LIF, CT-1, and CNTF) were able to significantly increase the CSC population in HMECs, pointing to their potential role as microenvironmental cytokines capable of promoting tumor progression through STAT3." (PMID 32023849, 2020).